BACH2 (BACH transcriptional regulator 2)
Diseases named in the same sentence as BACH2 in open-access papers (continued):
Sharing a sentence is not in itself a finding about the gene and the disease.
glioma (2 papers, 2020 to 2022). A benign or malignant brain and spinal cord tumor that arises from glial cells (astrocytes, oligodendrocytes, ependymal cells). "Interaction of BTB and CNC homolog 2 (BACH2) with fused in sarcoma (FUS) promoted glioma progression via transcriptional inhibition of TSLNC8." (PMID 32892482, 2020). "The downregulation of BACH2 significantly inhibits the viability, migration and invasive ability of glioma cells and promotes glioma cell apoptosis, suggesting that BACH2 may act as an oncogene." (PMID 32892482, 2020). "In glioma, studies have indicated that FUS can interact with BACH2 (BTB domain and CNC homologue 2), thus promoting glioma progression." (PMID 35586206, 2022). "In this study, the dual knockdown of BACH2 and FUS was found to exhibit stronger inhibition of the malignant behaviour of glioma cells, indicating that the interaction enhanced the cancer‐promoting effect." (PMID 32892482, 2020). "The present study investigated the expression of endogenous BACH2, FUS, TSLNC8 and miR‐10b‐5p in glioma tissues and cells." (PMID 32892482, 2020). "We demonstrated that the interaction between BACH2 and FUS promoted glioma progression via transcriptional inhibition of TSLNC8." (PMID 32892482, 2020). "Compared with NBTs, the expression of BACH2 and FUS was significantly increased in glioma tissues and with increasing pathological grade." (PMID 32892482, 2020). "Here, we investigated the endogenous expression of BTB and CNC homolog 2 (BACH2), fused in sarcoma (FUS), TSLNC8 and microRNA (miR)‐10b‐5p in glioma cells and tissues." (PMID 32892482, 2020). "The protein expression of BACH2 and FUS in different grades of glioma tissues and HA cells and U87 and U251 glioma cells was detected by western blotting." (PMID 32892482, 2020). "The functions of BACH2, FUS and TSLNC8 were further clarified by subcutaneous xenograft and orthotopic inoculation glioma models in nude mice." (PMID 32892482, 2020). "We studied the interaction between BACH2 and FUS and its contribution to glioma progression." (PMID 32892482, 2020). "Moreover, compared with HA cells, a significant upregulation of BACH2 and FUS protein expression was found in both U87 and U251 glioma cells." (PMID 32892482, 2020). "This demonstrated that the interaction between BACH2 and FUS enhanced the negative regulation of TSLNC8 by BACH2, thus facilitating the viability, migration and invasion of glioma cells and the inhibition of glioma cell apoptosis." (PMID 32892482, 2020). "An immunofluorescence assay was used to detect the localisation of BACH2 and FUS in glioma cells." (PMID 32892482, 2020). "BACH2 and FUS/TSLNC8/miR‐10b‐5p/WWC3 axis is responsible for glioma development and could serve as a potential target for glioma therapies." (PMID 32892482, 2020). "Our results indicate that the BACH2 and FUS/TSLNC8/miR‐10b‐5p/WWC3 axis is responsible for glioma development and could serve as a potential target for the development of new glioma therapies." (PMID 32892482, 2020). "Interestingly, the interaction between BACH2 and FUS may represent a novel target for the treatment of glioma." (PMID 32892482, 2020). "Taken together, these results indicate that BACH2 and FUS interaction enhanced the inhibition of the protein levels of WWC3 and YAP phosphorylation, TSLNC8 promoted the protein levels of WWC3 and YAP phosphorylation via miR‐10b‐5p and affected the malignant biological behaviour of glioma cells." (PMID 32892482, 2020). "However, the expression of BACH2 in gliomas has not been well‐studied." (PMID 32892482, 2020).
lupus nephritis (2 papers, 2019 to 2020). Glomerulonephritis in the context of systemic lupus erythematosus. "The Bach2-deficient mice also had elevated histopathologic indexes of lupus nephritis, as judged by their hypercellularity score and the percentage of proliferating glomeruli." (PMID 31819031, 2019). "Thus, the IgG autoantibodies that are enriched in Bach2-deficient mice appear to be sufficient to drive lupus nephritis." (PMID 31819031, 2019).
lymphoid neoplasm (2 papers, 2017 to 2023). A neoplasm composed of a lymphocytic cell population which is usually malignant (clonal) by molecular genetic and/or immunophenotypic analysis. "Many studies have examined the role of BACH2 in lymphoid neoplasms in relation to its critical actions in the B lymphocyte development and ontogeny, particularly as a tumor suppressor gene." (PMID 28924457, 2017). "Therefore all were selected for further functional analysis together with BACH2 and PRDM1, which had been implicated as TSG in lymphoid tumours and are positioned within the 6q15-6q21 deletion hot-spot." (PMID 36670235, 2023).
malaria (2 papers, 2018 to 2025). Malaria is a serious and sometimes fatal disease caused by a parasite that commonly infects a certain type of mosquito which feeds on humans. "Our results indicate that BACH2 either has a minor role in disease outcome during malaria and VL or compensatory mechanisms for BACH2 function are effectively activated following infection with the protozoan parasites that cause these diseases." (PMID 30459773, 2018). "Furthermore, T cell intrinsic BACH2 was needed for efficient expansion of CD4+ T cells during experimental malaria in this immunological setting." (PMID 30459773, 2018). "Furthermore, T cell intrinsic BACH2 is needed for efficient expansion of Th1 and Tr1 cells during experimental malaria." (PMID 30459773, 2018).
non-Hodgkin lymphoma (2 papers, 2011 to 2019). Distinct from Hodgkin lymphoma both morphologically and biologically, non-Hodgkin lymphoma (NHL) is characterized by the absence of Reed-Sternberg cells, can occur at any age, and usually presents as a localized or generalized lymphadenopathy associated with fever and weight loss. "Loss of heterozygosity for BACH2, a transcription repressor gene, has been detected in non-Hodgkin's lymphomas." (PMID 21931686, 2011). "Moreover, several reports pinpointed BACH2 as a candidate tumor suppressor gene in the B cell compartment by showing frequent loss of heterozygosity in non-Hodgkin lymphomas and a reduction of clonogenicity with increased sensitivity to apoptosis in BACH2 over-expressing Raji cells." (PMID 30654767, 2019).
primary immunodeficiency (2 papers, 2022 to 2024). "A new syndrome termed ‘BACH2-related immunodeficiency and autoimmunity’ (BRIDA) appears to be a monogenic primary immunodeficiency resulting from novel deleterious heterozygous point mutations in BACH2." (PMID 38891024, 2024).
promyelocytic leukemia (2 papers, 2013 to 2024). "In accordance with the preceding interpretation, a study reported the recruitment of BACH2 upon oxidative stress in promyelocytic leukemia nuclear (PML) nuclear bodies." (PMID 23936317, 2013).
ulcerative colitis (2 papers, 2018 to 2024). An inflammatory bowel disease involving the mucosal surface of the large intestine and rectum. "The differentially expressed genes (DEGs) were significantly enriched in target genes such as Bach2 according to the ulcerative colitis gene expression data, and signal transduction was markedly improved." (PMID 38459508, 2024).
acute leukemia (1 paper, 2023). A clonal (malignant) hematopoietic disorder with an acute onset, affecting the bone marrow and the peripheral blood. "Apart from SOX4, BACH2 also holds important implications for human acute leukemia as it represents one of the few conserved upregulated genes in myeloid and lymphoid disease." (PMID 36517672, 2023).
airway hyperresponsiveness (1 paper, 2016). "Moreover, pulmonary fibrosis was detected in the lungs of Bach2-deficient mice on Masson's trichrome staining, and methacholine-induced airway hyperresponsiveness was induced in the Bach2-deficient mice." (PMID 27581382, 2016).
allergic rhinitis (1 paper, 2025). Inflammation of the nasal mucous membranes caused by an IgE-mediated response to external allergens. "Recent research indicates that Bach2 regulates Th2 immune response activity, influencing susceptibility to allergic rhinitis." (PMID 40904186, 2025).
Arterial thrombosis (1 paper, 2023). The formation of a blood clot inside an artery. "Of these, six genes were most strongly associated with both venous and arterial thrombosis: G0S2, BCL2A1, TNFAIP6 (upregulated), CLIC3, BACH2, and TXK (downregulated)." (PMID 37035297, 2023).
autoimmune polyglandular syndromes (1 paper, 2021). "In conclusion, BACH2 polymorphism confers susceptibility to polygenic autoimmune polyglandular syndromes." (PMID 33966174, 2021).
brain tumor (1 paper, 2009). "Besides the thirteen Akv MLV integration sites, RTCGD contains one Moloney MLV integration site within in the Bach2 gene, which is derived from a brain tumor in the mutated C57BL/6 (Ink4a/Arf (-/-)) strain." (PMID 19159451, 2009).
cardiac hypertrophy (1 paper, 2022). "This study aims to explore the detailed role and underlying mechanisms of BACH2 in cardiac hypertrophy and failure." (PMID 36105283, 2022). "In this study, we found that the expression of BACH2 was remarkably downregulated in hypertrophic hearts of murine and humans, suggesting a potential role of BACH2 in the regulation of cardiac hypertrophy and failure." (PMID 36105283, 2022). "Systemic or cardiac-specific knockdown of Bach2 worsened the cardiac hypertrophy and failure phenotype in mice." (PMID 36105283, 2022). "When compared to wild type control mice, conventional heterozygous Bach2-knockout mice displayed a severer cardiac hypertrophy phenotype, such as more significant increases in HW/BW ratio, LV wall thickness and Bnp gene expression at 4–5 weeks after TAC." (PMID 36105283, 2022). "These in vivo and in vitro studies showed that depletion of BACH2 aggravated the progress of cardiac hypertrophy and failure." (PMID 36105283, 2022). "Both in vivo and in vitro data collectively indicated that overexpression of BACH2 played an inhibitory role in the development of cardiac hypertrophy." (PMID 36105283, 2022). "This study aims to explore the role of BACH2, a member of the basic region leucine zipper transcription factor family, in cardiac hypertrophy and failure." (PMID 36105283, 2022). "Next, we determined the expression level of BACH2 in mice hearts with TAC-induced cardiac hypertrophy and failure." (PMID 36105283, 2022). "Systemic or cardiac specific knockdown of Bach2 worsened the cardiac hypertrophy and failure phenotype in mice after TAC." (PMID 36105283, 2022). "Further assays showed that BACH2 bound to the promotor region of Akap6 at the -600 to -587 site and repressed its expression, which functioned as a crucial scaffold for cardiac hypertrophy and failure signaling pathways." (PMID 36105283, 2022). "In conclusion, our study demonstrates that BACH2 plays an important role in the regulation of cardiac hypertrophy and failure." (PMID 36105283, 2022). "To define the functional role of BACH2 in regulation of cardiac hypertrophy and failure, we overexpressed BACH2 in TAC-induced cardiac hypertrophic mice with adeno-associated virus 9 (AAV9) encoding mouse Bach2 by the tail vein injection." (PMID 36105283, 2022). "Taken together, our findings demonstrated that BACH2 plays a crucial role in the regulation of cardiac hypertrophy and failure and can be a potential therapeutic target in the future." (PMID 36105283, 2022). "Mice with global or cardiac-specific knockout of Bach2 as well as BACH2 overexpression by AAV9 were constructed to verify the function of BACH2 in cardiac hypertrophy and failure." (PMID 36105283, 2022). "Both in vivo and in vitro results showed that upregulation of BACH2 significantly inhibited the development of cardiac hypertrophy, whereas BACH2 knockdown exacerbated the progression of cardiac hypertrophy." (PMID 36105283, 2022). "For the treatment of clinical cardiac hypertrophy and heart failure, BACH2 may serve as a potential valuable intervention target in the future." (PMID 36105283, 2022). "Moreover, our current study showed that natural product myricetin ameliorated cardiac hypertrophy and failure partially via up-regulating BACH2." (PMID 36105283, 2022). "Given the results of the inhibitory effect of BACH2 overexpression on cardiac hypertrophy, we tried to screen natural products that could up-regulate BACH2 expression." (PMID 36105283, 2022). "Overexpression of BACH2 protected the mice from TAC-induced cardiac hypertrophy and failure." (PMID 36105283, 2022). "We here found that myricetin could inhibit cardiac hypertrophy in wild type mice and cardiomyocytes, but not in Bach2-deficient hearts and cardiomyocytes." (PMID 36105283, 2022). "However, the role of BACH2 in cardiac hypertrophy and failure is still unknown." (PMID 36105283, 2022).
cutaneous T-cell lymphoma (1 paper, 2024). "The BACH2 gene is a transcription factor associated with cutaneous T-cell lymphoma, and its expression is suppressed in CD4-positive T cells." (PMID 38545443, 2024).
fatty liver disease (1 paper, 2025). A reversible condition wherein large vacuoles of triglyceride fat accumulate in liver cells via the process of steatosis. "The protective effect of Bach2 deficiency against the development of fatty liver disease warrants further investigation." (PMID 41169388, 2025). "Taken together, these data suggest that Bach2-deficient mice are protected from HFD-induced fatty liver disease." (PMID 41169388, 2025). "However, the molecular and immunological mechanisms that underlie Bach2 action in HFD-induced fatty liver disease still need to be investigated." (PMID 41169388, 2025). "The finding that elimination of the inflammatory inhibitor, Bach2, exerts a protective effect in fatty liver disease appears to be initially intriguing." (PMID 41169388, 2025). "The elimination of the repressor effect of Bach2 in our mouse model could therefore lead to the reactivation of immune response, which in turn prevents the development of liver steatosis." (PMID 41169388, 2025). "The direct effects of Bach2 knockout in resident liver cells may also play a role in preventing fatty liver disease, although the data regarding this is limited." (PMID 41169388, 2025).
glioblastoma multiforme (1 paper, 2020). "BACH2 has known tumor immunosuppressive capacity, and P4HB upregulation may be involved with glioblastoma multiforme as noticed for integration sites recovered from the ART-treated individuals, thus suggesting that oncogenic genes may play a role in the overlap." (PMID 32970634, 2020).
Hypertension (1 paper, 2022). The presence of chronic increased pressure in the systemic arterial system. "We first examined human hearts to determine whether the expression of BACH2 changed in hypertrophic hearts with pre-diagnosed hypertension compared with the control hearts without known cardiovascular diseases." (PMID 36105283, 2022).
hyperthyroidism (1 paper, 2014). Overactivity of the thyroid gland resulting in overproduction of thyroid hormone and increased metabolic rate. "Borderline significant signals were observed at BACH2- rs10944479 with a higher risk of increased TSH levels as well as overt hyperthyroidism (P = 0.011 and P = 0.012), and at the KALRN-rs2010099 SNP with a lower risk of decreased TSH levels (P = 0.010)." (PMID 24586183, 2014).
immunoglobulin deficiency (1 paper, 2018). "BACH2 haplo-insufficiency has been associated with lymphocyte-maturation defects leading to immunoglobulin deficiency and intestinal inflammation." (PMID 30586396, 2018).
influenza infection (1 paper, 2022). "Next, we investigated whether Bach2-deficiency in regulatory T cells altered the activation and expansion of effector CD8 and CD4 T cells during an influenza infection." (PMID 36033397, 2022).
irritable bowel syndrome (1 paper, 2024). Irritable bowel syndrome (IBS) is a chronic functional condition of the lower gastrointestinal (GI) tract characterized by abdominal pain or discomfort and disordered bowel habit (diarrhea, constipation, or fluctuation between the two). "BACH2-promoter methylation is associated with irritable bowel syndrome (IBS)." (PMID 38891024, 2024).
keloid (1 paper, 2025). An irregularly shaped, elevated mark on the skin caused by deposits of excessive amounts of collagen during wound healing. "By utilizing keloid sample data for TF analysis and target gene prediction, we identified three potential master TFs (FOXP1, FOSL2, and BACH2) that may regulate the expression of these five SE-associated genes in keloids." (PMID 40702440, 2025). "By predicting the major TFs upstream of the identified SE-associated genes, it was discovered that FOSL2, BACH2, and FOXP1 were not only highly enriched in keloid fibroblasts but also significantly upregulated in keloids." (PMID 40702440, 2025). "We also found that FOSL2, BACH2, and FOXP1 were significantly highly expressed in the keloid group, and the results were as shown in the heatmap." (PMID 40702440, 2025).
liver fibrosis (1 paper, 2024). "The exploration extends to liver fibrosis, where exosomal ncRNAs, particularly lncRNA WAC-AS1, wield influence over HSCs, modulating BACH2 and instigating ferroptosis." (PMID 38385027, 2024).
metabolic dysfunction-associated steatotic liver disease (1 paper, 2025). Metabolic dysfunction-associated steatotic liver disease (MASLD, formerly known as nonalcoholic fatty liver disease or NAFLD) is a type of liver disease that is not caused by alcohol. "Considering the rapid increase in the prevalence of metabolic dysfunction-associated steatotic liver disease (MASLD, previously known as nonalcoholic fatty liver disease (NAFLD)) in humans, this novel aspect of Bach2 function deserves further attention." (PMID 41169388, 2025).
myocardial infarction (1 paper, 2023). Gross necrosis of the myocardium, as a result of interruption of the blood supply to the area, as in coronary thrombosis. "In addition, BACH2 is referred as a candidate gene in a profiling study of patients with myocardial infarction." (PMID 37160609, 2023). "Interestingly, Bach2 KO mice showed increased liver enzyme activities, namely aspartate transaminase, considered to be a myocardial infarction biomarker in humans." (PMID 37160609, 2023).
neuroblastoma (1 paper, 2020). Neuroblastoma (NB) is the most common solid, extracranial childhood tumor. "In addition, OTX1 and OTX2 have been identified as two possible molecular markers for sinonasal carcinomas and olfactory neuroblastomas, whereas BACH2 is associated with the neuronal differentiation of N1E-115 neuroblastoma cells." (PMID 32391054, 2020).
papillary thyroid cancer (1 paper, 2021). "Moreover, hsa_circ_0001627, a circRNA derived from exon 2 of the BACH2 gene, has been proven to be highly expressed in papillary thyroid cancer (PTC) tissues and facilitates the malignant progression of PTC28." (PMID 33875646, 2021).
parasitemia (1 paper, 2018). "In summary, we showed BACH2 is an important intrinsic factor in CD4+ T cells during differentiation in vitro and during parasitic infection." (PMID 30459773, 2018).
retinal disease (1 paper, 2012). "Based on putative function and/or involvement in retinal disease, we selected 16 genes – Bach2, Cdr2, Dusp12, Esrrb, Gpsm2, Haus1, Kdm5b, Lman1, Lrp11, Lrrc2, Ncoa2, Plekha2, Ppargc1b, Trim36, Wisp1 and Zdhhc14." (PMID 22511886, 2012).
sarcoidosis (1 paper, 2021). Sarcoidosis is a multisystemic disorder of unknown cause characterized by the formation of immune granulomas in involved organs. "Only one study found a possible role for BACH2 in sarcoidosis patients." (PMID 33903979, 2021).
scoliosis (1 paper, 2025). A congenital or acquired spinal deformity characterized by lateral curvature of the spine. "BACH2 and HLA-G shared the same variant with CD28 on CD28+ CD45RA+ CD8+ T cell which could increase the risk of scoliosis." (PMID 40270514, 2025).